ERBB2 (erb-b2 receptor tyrosine kinase 2)
Diseases named in the same sentence as ERBB2 in open-access papers (continued):
Sharing a sentence is not in itself a finding about the gene and the disease.
tumor (continued). "Human epidermal growth factor receptor 2 (HER2; also called Her-2/neu or ErbB2) is a member of the transmembrane epidermal growth factor receptor family and is one of the most studied tumor-associated antigens (TAAs) for cancer immunotherapy." (PMID 24919843, 2014). "Should such Src activation or Src mutation be identified in such tumor samples, the results from this report support subsequent efforts to perform clinical trials of a combination of ERBB2 inhibition and Src inhibition." (PMID 25350844, 2014). "In the MMTV/ErbB2 mouse model, β1-deficient tumor metastasis to the lung was delayed and was correlated with downregulation of tyrosine phosphorylation of Src, p130Cas and paxillin, all integrin-coupled signaling partners." (PMID 25606594, 2014). "Tumour ErbB2-IR was significantly associated with the downstream signalling molecule phosphorylated-Akt and with the cell proliferation marker Ki-67." (PMID 25215939, 2014). "In the tumour samples, ErbB2-IR was significantly associated with both the cell proliferation marker Ki67 and the immunoreactivity of pAkt, the phosphorylated form of the survival factor Akt." (PMID 25215939, 2014). "There was a weak association of tumour ErbB2-IR with the Gleason score at diagnosis, consistent with the literature." (PMID 25215939, 2014). "ERBB2 is a member of the EGFR family that is associated with increased proliferation of tumor cells." (PMID 24926380, 2014). "Neither of the SNPs was significantly associated with primary tumor diameter, axilliary nodal status, histology, tumor grade, ER or PR expression, or ERBB2 amplification." (PMID 25036186, 2014). "The emergence of sophisticated genomic methodologies like next-generation sequencing enabled high-throughput detection of known and novel oncogenic mutations, and in particular revealed the presence of activating mutations of ERBB2 in a variety of tumor types." (PMID 23630663, 2013). "mRNA of the ERBB2 gene was increased by 2.4-fold (P=0.044) in the tumor samples with the variant C/C and C/T MIR125A variants, compared with the T/T variant." (PMID 23420759, 2013). "Most conventional strategies are designed to combat the gain-of-function associated with oncogenes (e.g., ERBB2), and all but ignore tumor suppressor genes due to the inherent complexities in restoring a loss-of-function(s) mutation within a tumor cell." (PMID 24202319, 2013). "Ablation of endogenous Erbb3 in mammary epithelial cells caused a decrease in ERBB2 induced tumor incidence from 93.3% to 6.7%." (PMID 23593223, 2013). "Since AR is frequently expressed in ERBB2 amplified tumors, we asked how the loss of AR signaling would affect tumor incidence and progression in this cohort." (PMID 23593223, 2013). "Although activating mutations of ERBB2 were identified in various tumor types and several potential therapeutic options are at hand, specific screening for these lesions has not been translated into clinical routine yet." (PMID 23630663, 2013). "When the Human Epidermal growth factor Receptor 2 (HER2, also known as ErbB2) is used as a tumour marker in the community of clinical oncologists, 'HER2' is related to the diagnostic terms." (PMID 23046572, 2012). "While in humans amplification/over-expression of ErbB2 is oncogenic, in animals activating transmembrane ErbB2 mutations are required for tumor growth." (PMID 22279592, 2012). "Again, these observations reinforce the concept that loss of FAK in ErbB2 tumour cells renders them at a competitive disadvantage in their capacity to colonize the metastatic site." (PMID 22373082, 2012). "Consistent with reduction in c-Src activation and p130Cas-initiated signaling, the FAK-deficient ErbB2 tumour cells exhibited a proliferative defect relative to their FAK-proficient counterparts." (PMID 22373082, 2012).
tumor (continued). "The demonstration of a possible association between primary tumor size (one of the two most important prognostic factors) and the number of masses with the cat ERBB2 variant haplotypes reveal the importance of the analysis of this gene in veterinary medicine." (PMID 22489125, 2012). "Collectively these observations indicate that loss of FAK in established ErbB2 tumour cells impacts on a combination of cell proliferation, migration, invasion and spreading." (PMID 22373082, 2012). "No improvement in precision of class partition was achieved on inclusion of either PIK3CA or ERBB2 aberrations as additional layers of information to the group of tumor samples with gene mutations." (PMID 23226389, 2012). "To test this possibility, we performed immunoblot analyses with FAK- and ErbB2-specific antisera on lysates from either parental MMTV-NDL2-5 tumours or tumours homozygous for the FAK conditional alleles." (PMID 22373082, 2012). "Considering the role of the oncogenic ErbB2-ErbB3 unit, it will be interesting to determine if activating ErbB3 mutations are uncovered in tumours that have low ErbB2 expression." (PMID 23202898, 2012). "The majority of p27 in tumor cells is regulated by ubiquitin degradation, and an upregulation of p27 has been associated with downregulation of skp2 via erbB-2 or EGFR inhibition." (PMID 22322523, 2012). "In the present study, we clearly demonstrated that high expression of ErbB2 in tumor cells were associated with enhanced sensitivity to the antiproliferative and antitumor effects of AST1306." (PMID 21789172, 2011). "Integrin α5 up-regulation was identified as the molecular mechanism by which E-cadherin loss promotes tumor progression and ERBB2-mediated transcriptional up-regulation of the α5β1 promotes tumor cell survival under adverse conditions." (PMID 21752283, 2011). "There were no significant statistical direct correlations between erbB2 CN and these clinical features, except for tumor location when associated with erbB2 CN >2 (P = 0.05)." (PMID 21481261, 2011). "In the case of TXNRD1, associations were observed with tumor grade and pT stage, hormone receptor status and ERBB2 status." (PMID 20584310, 2010). "Recent studies have shown that MUC4 is implicated in modulation of ErbB2 signalling, in repression of apoptosis, in regulation of cell adhesion, in promoting tumor progression and metastasis, and in multidrug resistance processes." (PMID 20553613, 2010). "In control tumors, ErbB2 was phosphorylated at tyrosine 1221/1222 and is associated with high tumor grade and with shorter disease-free survival and overall survival." (PMID 19878607, 2009). "It has been reported that ERRα expression is associated with an adverse, aggressive tumor phenotype correlating with ERBB2 (HER2, NEU) overexpression." (PMID 19462000, 2009). "Switching-off ERBB2 expression by tetracycline administration causes a rapid and complete tumour remission, demonstrating a high degree of ‘ERBB2 dependence’." (PMID 18454161, 2008). "The 62-gene Ox-E/ER signature inversely correlated with tumor PR status and mRNA levels, and was positively associated with ERBB2 over-expression." (PMID 18631401, 2008). "Tumours arising in the MMTV-c-ErbB2 mice usually display mutations in the wild type rat c-ERBB2 transgene resulting in a constitutively activated form of ErbB2." (PMID 18700973, 2008). "Surprisingly, trastuzumab caused only a very weak delay in tumour growth, which is in sharp contrast to the excellent efficiency of Atc-mediated ERBB2 downregulation." (PMID 18454161, 2008). "In the same tumours trastuzumab caused translocation of ERBB2 from the membrane to the cytoplasm but tumour growth was only slightly delayed." (PMID 18454161, 2008).
tumor (continued). "Overexpression of the human transmembrane tyrosine kinase growth factor receptor (HER-2), characteristic of the ERBB2 group, has been associated with more aggressive forms of tumor and with resistance to endocrine therapies." (PMID 16846532, 2006). "Most tumor-derived cell lines express significant mouse ErbB3-encoded protein, in addition to high levels of the rat c-neu/ErbB2 transgene." (PMID 16168116, 2005). "To study cross-species functional interactions between the rat c-neu/ErbB2 transgene and mouse ErbB3, we evaluated tumor and tissue expression in vivo, ligand-associated interactions, and signaling in vitro." (PMID 16168116, 2005). "Gene amplification and ErbB2 overexpression have been observed in many human tumours of epithelial origin and have been linked with cancer development and progression." (PMID 15812545, 2005). "Because ErbB-2 has been implicated in the activation of Akt, we investigated the association between P-Akt and ErbB-2 and its prognostic significance in tumours with known ErbB-2 expression levels." (PMID 15987444, 2005). "CC homozygous patients also showed trends for association with larger tumour size, low oestrogen receptor content, aneuploidy and amplified ErbB2 status, all of which are known features of poor prognosis." (PMID 14735187, 2004). "Associations between ERBB2 expressions and biological or clinical factors were observed only if tumours with staining category 1+ were grouped together with tumours showing staining categories 2+ and 3+." (PMID 15545967, 2004). "Associations between ERBB2 expression and clinical factors were observed only if tumours with staining category 1+ were grouped together with tumours showing staining categories 2+ and 3+." (PMID 15545967, 2004). "Although liquid biopsies are increasingly being used in clinical oncology, the association between tumor and circulating tumor DNA (ctDNA) ERBB2 status and ctDNA monitoring for early response and resistance are unknown." (PMID 40512191, 2025). "In ErbB2 (a driver oncogene) positive breast cancer cells, ECD controls ErbB2 mRNA export and stability by regulating the decreased expression of herstatin (a tumor suppressor splice variant) and increased expression of the Δ16HER2 variant (a pro-oncogenic splice variant)." (PMID 41308033, 2025). "Data from DESTINY trials demonstrate that HER2 overexpression (IHC3+) remains the strongest predictor of response, while ERBB2 mutations show variable sensitivity and may inform future tumor-agnostic indications." (PMID 40828885, 2025). "ERBB2 activating mutations across all domains were largely clonal (ranging from 73.1%–92.0% of ERBB2 mutations across cancer types), indicating they are often likely truncal in the tumor types studied." (PMID 40178042, 2025). "However, when comparing tumours with ERBB2 mutations and ERBB2 amplification, higher TMB levels were observed in tumours with ERBB2 amplification." (PMID 40650126, 2025). "Copy-number gains (e.g., ERBB2 amplification) and certain structural variants generally require higher ctF for reliable detection, and plasma-based tumor mutational burden (bTMB) can be biased downward when few tumor molecules are captured." (PMID 41008912, 2025). "Interestingly, this tumor showed an ERBB2 mutation (p.Leu755Ser) and a gain of one copy at 17q, including the ERBB2 gene, as demonstrated by sequencing and FISH, respectively." (PMID 39936988, 2025).
tumor (continued). "Three patients had at least one activating KRAS alteration and/or KRAS amplification detected in all samples, with the ERBB2 amplification occurring in the last sample, notably corresponding to an increase in tumor shed, as measured via the maximum variant allele frequency (maxVAF) in the sample." (PMID 38406801, 2024). "However, several SNPs are reported for the canine ERBB2, some associated with specific tumor subtypes." (PMID 39696035, 2024). "Consistent with the inhibitor studies, stable silencing of Nrf2 supressed proliferation, glucose consumption, and the basal and maximal OCRs in Cpt1a-deficient ErbB2+ tumor cells, but had minimal effects on wild-type cells, arguing that Nrf2 is present but not essential in these cells." (PMID 39097623, 2024). "Clinical and tumor characteristics associated with BC and ERBB2-low or ERBB2-negative status." (PMID 38517439, 2024). "Moreover, of the cell-free deoxyribonucleic acid (cfDNA) extracted from liquid biopsy mutated-ERBB2 was considered the circulating-tumor deoxyribonucleic acid (ctDNA) of this tumor." (PMID 38389074, 2024). "Thus, the concordance rate of ERBB2 mutation status between plasma cfDNA and tumor tissue was 83% (5/6)." (PMID 38287892, 2024). "For five of these patients, the ERBB2 mutation identified in plasma could also be detected in tumor tissues (L755S for patient #17, V777L for patient #162, V777L for patient #167, L869R for patient #227, and V777L for patient #229)." (PMID 38287892, 2024). "Similarly, in human studies, in which the expression of the ErbB receptors was correlated with the clinical tumor behavior, revealed that ErbB2 was mainly associated with aggressive and/or resistant prolactin-secreting PitNETs." (PMID 37109772, 2023). "ERBB2 gene amplification will result in the overproduction of ErbB2 protein, which can cause cells to grow and divide continuously, leading to uncontrolled cell division, one of the hallmarks of cancerous tumor progression." (PMID 36826044, 2023). "We also decided to retain ESR1 and ERBB2, since their mutation prevalence increased gradually from primary tumor to extracerebral metastases and brain metastases, an observation that may have therapeutic implications." (PMID 36980614, 2023). "This was expected as oncogene-enriched subtype tumours exhibited more aggressive tumour growth and had an increased expression of gene mutations involved in cell proliferation (ERBB2, SLC44A4, EPCAM, CLDN3, and CLDN4), cell differentiation (ELF3 and GPX2), and mucin production (KRT20)." (PMID 36723696, 2023). "In patient 2366, VAF for the SNP rs1309838194 in ERBB2 changed from around 50% (heterozygous at baseline time point) to 80% during follow-up, which indicated increased tumor-derived DNA in plasma and may be associated with disease progression." (PMID 35379811, 2022). "Interestingly, the expression scores of the multigene module reflecting HER2/ERBB2‐signaling significantly differ between the ultralow risk tumors as compared to the other ER‐positive tumor groups." (PMID 35179782, 2022). "The next-generation sequencing assay showed that the tumor had an ERBB2 mutation." (PMID 35875132, 2022). "Patients with HER2DX low-risk and ERBB2 mRNA-low or ERBB2 mRNA-medium tumours, the benefit from adjuvant pertuzumab might be very small, if any." (PMID 36374768, 2022). "Our study showed a varying pattern of ERBB2 mutations across different tumor types." (PMID 35911441, 2022). "Moreover, patients with higher m6ASig score were associated with higher microsatellite instability (MSI); higher PD-L1, CTLA4, and ERBB2 expressions; and greater tumor mutation burden (TMB)." (PMID 36193316, 2022).
tumor (continued). "Indeed, HER2-positive tumours harboured more mutations in the ERBB2 gene in those patients, who underwent more lines of treatment with anti-HER2-targeted drugs." (PMID 35158855, 2022). "Moreover, ERBB2 c.1899-2A>T with concurrent ERBB2 gene amplification were the mutations detected from baseline tumor and plasma samples of a stage IV LC patient (P07)." (PMID 36686783, 2022). "BC is classified into three main tumor subtypes rooted in enhancement in expression of either progesterone receptor (PR) or estrogen receptor (ER), and/or epidermal growth factor receptor 2 (ERBB2) gene mutation." (PMID 35877371, 2022). "The ERBB2 p.(Ile655Val) variant was detected in 40% of the tumours in this study." (PMID 35884448, 2022). "Proteins that contribute most strongly to proteotype-based classification include inositol polyphosphate-4-phosphatase, type II (INPP4B), cyclin-dependent kinase 1 (CDK1), and receptor tyrosine kinase 2 (ERBB2) are associated with estrogen receptor (ER) status, HER2 status tumor, and grade status." (PMID 34948142, 2021). "Numerous in vitro and in vivo studies, as well as studies on humans, prove that targeting overexpressed molecules, such as mucin 16 (MUC16), annexin 2 (ANXA2), receptor tyrosine-protein kinase erbB-2 (HER2/neu) causes high tumour cells toxicity and decreased tumour burden." (PMID 33800608, 2021). "Tumor stage (cT) was a significant factor for ERBB2 mutation (p = 0.044)." (PMID 33920322, 2021). "As a future direction, we recommend investigating the mechanism of the negative feedback loop to understand how HER2 overexpression induces EMT, and how EMT causes ERBB2 gene silencing, leading to the emergence of tumor cells resistant to HER2-targeted therapies." (PMID 34575017, 2021). "Thus, BsAb can be used as a component of the immunocytokine complex for the delivery of IFN-β to ErbB2-associated tumor cells, which would avoid the manifestation of side effects when IFN-β is administered as a single therapeutic." (PMID 34944558, 2021). "CMS subtype was significantly associated with tumor metastasis in the Erbb2 cohort (p = 0.004)." (PMID 35242697, 2021). "Thus, tumor-associated loss of CHIP can be viewed as an adaptive mechanism to relieve ErbB2 associated with Hsp90 of a bottleneck on its transit to the cell surface." (PMID 34439093, 2021). "The low consistency observed in blood samples may be due to high intratumor heterogeneity, which would cause variable amplification of the ERBB2 copy number in different tumor tissue sites." (PMID 33893247, 2021). "Likewise, mutational status of RAS, BRAF, and ERBB2, as well as tumor-sidedness, are clinically relevant to guide therapy options." (PMID 34805267, 2021). "While these data must be considered preliminary, this observation raises the question whether ERBB2 mutations are true drivers of tumor growth in CRC." (PMID 36046264, 2020). "To determine whether the tumor-associated antigens that were used for the synthesis of the branched multipeptide were indeed present on GL261 cells, we estimated the expression of the two tumor-associated antigens (ErbB2 and WT1) on GL261 cells." (PMID 32733437, 2020). "Tumor-associated antigens (e.g., ERBB2/HER2) are highly expressed in tumor and poorly expressed in normal tissues, so they may serve as therapeutic targets for some tumor types, but the disadvantage is that they may cause nonspecific immune responses." (PMID 32733937, 2020). "The latest results indicate that the clinical benefit of ERBB2 tyrosine kinase inhibitor, neratinib, may depend on the type of ERBB2 mutation and the type of tumor." (PMID 33117683, 2020). "In particular, CNV in ERBB2 was associated with aggressive tumor characteristics." (PMID 33298978, 2020).